MTOR (mechanistic target of rapamycin kinase)
Diseases named in the same sentence as MTOR in open-access papers (continued):
Sharing a sentence is not in itself a finding about the gene and the disease.
tumor (continued). "Mechanistic target of rapamycin (mTOR) activation is responsible for the promotion of tumor growth and metastasis." (PMID 33918514, 2021). "The expression of additional markers (AKT, SRC, mTOR, NF-κB, Ki-67) emphasized the aggressiveness of the tumor." (PMID 33313992, 2021). "Among others, PD-L1, ERG, Integrin-β5, Survivin, TGF-β, phosphorylated-TSC2 as well as partners of the MAP-kinase and mTOR pathways emerged as differentially expressed endpoints in tumor-derived EVs." (PMID 34155195, 2021). "The binding of osteoblastic N-cadherin to N-cadherin on tumor cells activates the mTOR signaling pathway to enhance the activation and proliferation of dormant tumor cells." (PMID 33869189, 2021). "By performing metabolomics analysis, we identified glutamine (Gln), an important amino acid, inducing resistance to 5FU-triggered tumor suppression of CRC-PC through activating mTOR pathway." (PMID 34712612, 2021). "TGF-β1-mediated upregulation of miR-494 in MDSCs supports tumor cells proliferation and metastasis by regulating the activity of MDSCs via targeting mTOR inhibitor PTEN." (PMID 35250965, 2021). "Inhibition of mTOR signaling successfully attenuated tumor growth in both models and prophylactic rapamycin reduced the incidence of ASCC formation in the transgenic mouse." (PMID 34062753, 2021). "Everolimus, a rapamycin analog, is an mTOR suppressor that can inhibit tumor cell compartment formation and angiogenesis." (PMID 34204169, 2021). "One of the main targets of antineoplastic therapy in RCC patients is the mTOR serine/threonine kinase, which forms the catalytic subunit of the complex molecular mTORC1 and is involved in numerous processes responsible for tumor progression." (PMID 33918154, 2021). "The PI3K/AKT/mTOR signaling pathway plays a crucial role in tumor formation, cell cycle progression, apoptosis, and survival." (PMID 34395292, 2021). "The results demonstrate that downregulation of phosphorylation AKT/mTOR is required for Salmonella-mediated CXCR4 expression in tumor cells." (PMID 34220311, 2021). "One of the major effects is the activation and phosphorylation of mammalian target of rapamycin (mTOR), involved in several molecular processes, that correlates with tumor progression and invasion." (PMID 33918154, 2021). "First, metformin activates adenosine monophosphate kinase (AMPK), which inhibits the mammalian target of Rapamycin (mTOR) and its downstream tumour proliferation effects." (PMID 33927955, 2021). "For tumor metabolism-related pathways, ICB and lenvatinib can inhibit tumor cell proliferation by downregulating glycolytic enzymes and reducing mTOR activity in tumor cells." (PMID 34568339, 2021). "We show that this change in the TME induces GS upregulation in adipocytes, increasing the production of Gln, which promotes resistance of tumor cells to 5FU chemotherapy, a process mediated by mTOR activation." (PMID 34712612, 2021). "Pharmacological inhibition of PI3K/mTOR blocks tumor growth and survival signaling in different tumor xenograft models." (PMID 33660194, 2021). "Tumor growth was slower in xenografts generated by mTOR-silenced MEC cells (p < 0.0001), when compared with tumors generated by control cells." (PMID 33479203, 2021). "Together, these data indicate that dual inhibition of ERK and mTOR pathways yielded a synergetic anti-tumor activity in NSCLC cells." (PMID 34421360, 2021). "In cancers, the PI3K/AKT/mTOR signaling pathway is involved in tumor cell growth, proliferation, invasion, and metastasis; endothelial cell growth; and angiogenesis, radiation sensitivity, apoptosis, and autophagy inhibition." (PMID 34204169, 2021).
tumor (continued). "To demonstrate the utility of this function, we analyzed the distribution of the mTOR subprocesses across the tumor and normal adjacent tissue from the TCGA datasets (variable: disease status)." (PMID 34179848, 2021). "The oncogenic PI3K/AKT/mTOR pathway regulates metabolic networks and promotes aerobic glycolysis in favor of tumor cells." (PMID 34831287, 2021). "Our experiments show that aloin-related PI3K/AKT/mTOR axis regulation inhibited the growth of tumor cells and induced autophagy." (PMID 34819120, 2021). "SLC15A4 is required for Toll-like receptor 7 (TLR7)- and TLR9-mediated type I interferon (IFN-I) production in plasmacytoid dendritic cells (pDCs) by the mTOR pathway, highlighting its role in regulating the immune response in the tumor microenvironment." (PMID 34168674, 2021). "The PI3K/AKT/mTOR signaling pathway is commonly activated in solid tumors and is critical for tumor progression, metastatic spread, and therapeutic resistance." (PMID 33807608, 2021). "KD stimulates the AMPK signaling pathway, the tumor suppressor activity, which leads to mTOR signaling inhibition." (PMID 34287243, 2021). "Herein, radiosensitization by metformin has been attributed to the PI3K/AKT/mTOR pathway or through improved oxygenation, reduces tumor hypoxia." (PMID 34209135, 2021). "BEZ235, a dual inhibitor of PI3K and mTOR, reduced the tumor volume in a mouse model of PC, which was mediated by PTEN loss." (PMID 34452154, 2021). "It has been reported that miR-21-3p promoted cell proliferation, migration and invasion through regulating TSC2/mTOR pathway, and augmented tumor proliferation via PI3K/AKT pathway." (PMID 34388112, 2021). "Autophagy and NETs are able to suppress tumor activity through specific mechanisms including mTOR signaling pathway and produced ROS of neutrophils, respectively." (PMID 34660642, 2021). "RHEB binds and activates the mechanistic target of rapamycin (mTOR), a regulator of tumor cell growth, survival, and metabolism." (PMID 34771475, 2021). "Previous studies have shown that immunosuppressor rapamycin (macrolides antibiotics) inhibits tumor progression through targeting mammalian target of rapamycin (mTOR)." (PMID 34899336, 2021). "It downregulated the expression of downstream proteins phosphorylated Akt (p-AKT), phosphorylated mTOR (p-mTOR), NF-κB, and phosphorylation of inhibitor of kappa B (p-IκB), which play a regulatory role in autophagy, apoptosis, and tumor growth." (PMID 33494431, 2021). "Deletion and inactivation of PTEN gene and overexpression of PI3K gene can stimulate Akt activation, and promote tumor growth, invasion and metastasis through a variety of downstream effectors (including mTOR)." (PMID 33865336, 2021). "Blocking mTOR signaling can restore the sensitivity of several anti-tumor drugs including crizotinib, vemurafenib, and erlotinib." (PMID 33732706, 2021). "This tumor suppressor role was mediated by inhibition of the mTOR pathway, as shown by dephosphorylation of mTOR on serine 2448 and a decrease in its pathway-associated targets HIF-1α, Sox2 and c-Myc." (PMID 34768967, 2021). "GLN uptake promoted both GLS and GLS2 mRNA expression after 6 h of stimulation, which promoted the use of GLN by tumor cells while stimulating downstream mTOR signaling to promote tumor progression." (PMID 34503536, 2021). "Increasing evidence demonstrates that Notch1 regulates PI3K-Akt-mTOR signalling in tumours, although many details are still emerging." (PMID 34495871, 2021). "The combination of HSP90 inhibitors to enhance endoplasmic reticulum stress with mTOR inhibition results in tumor shrinkage in a murine MPNST model." (PMID 34502310, 2021). "When NSCLC patient tissue samples were examined for PI3K, total mTOR, and phosphorylated mTOR through IHC, all showed positivity in the majority of the tumor cells." (PMID 33833996, 2021).
tumor (continued). "In turn, the downregulation of mTOR activity in T cells impairs their metabolic reprogramming and function and facilitates tumor immune escape." (PMID 35250965, 2021). "Mechanistically, PDL1 blockade has been shown to decrease glycolysis in tumor cells by inhibiting mTOR activity and reduced the expression of glycolytic enzymes." (PMID 34073734, 2021). "A study with HNSCC cell lines demonstrated beneficial effect of mTOR inhibitors plus cetuximab in the treatment of tumor with low EGFR expression or those that acquired resistance due to cetuximab/cisplatin." (PMID 34490084, 2021). "The increased proliferative potential of tumor cells are frequently supported by AKT/mTOR signaling that contributes to the upregulated protein synthesis and cellular growth." (PMID 34575486, 2021). "The aim of this study was to investigate the underlying mechanism of novel dual PI3K/mTOR inhibitor, Apitolisib (GDC-0980), in A-172 and U-118-MG GBM tumour cell line suppression." (PMID 34768941, 2021). "mTOR-mediated upregulation of granulocyte colony-stimulating factor (G-CSF) in tumor-initiating cells (TICs) dictates the recruitment of pro-tumorigenic MDSCs into TME." (PMID 35250965, 2021). "Using IHC, we found that CRC tumors had higher levels of mTOR activation (p-mTOR) than adjacent non-tumor tissues." (PMID 33897695, 2021). "In this study, combined blocking of TIGIT and PD-1 showed further tumor control, decreased reduction of key factors in glucose metabolism, and significantly inhibit Akt/mTOR signaling pathway compared with either single blocking in tumor-bearing mice." (PMID 34659197, 2021). "AKT is a key regulator of PI3K/AKT/mTOR pathway, and its abnormal activation can significantly promote progression of tumor, it is also an important target for clinical treatment." (PMID 34322387, 2021). "We have shown that chloroquine alone suppresses tumor cells’ viability and proliferation and increases their cytotoxicity and apoptosis; these effects are augmented when chloroquine is added to mTOR inhibitors." (PMID 34944946, 2021). "The phosphorylation of mTOR is considered a specific marker for tumour progression and, in turn, mediates the activation of downstream target factors, such as S6K and 4E-BP1." (PMID 34439105, 2021). "We have previously reported that dual PIK3/mTOR pharmacological inhibition using bimiralisib has in vitro and in vivo anti-tumor activity and that it induces transcriptional changes in DLBCL cell lines." (PMID 33923420, 2021). "The binding of insulin or free insulin-like growth factor IGF-1 to specific tyrosine kinase receptors can activate the insulin/IGF-1-PI3K-Akt-mTOR signaling pathway and enhance glycolysis and glutamine breakdown, thereby promoting tumor cell proliferation." (PMID 33918992, 2021). "Mammalian target of rapamycin, mTOR, is typically upregulated in tumor cells to induce proliferation." (PMID 34823532, 2021). "These drugs seem to act directly on tumor cells by inhibiting glycolysis and mTOR signaling and activating mechanisms that eventually drive to apoptosis." (PMID 34692471, 2021). "Rapamycin was observed to reverse mTOR-mediated tumor cell resistance against herpes simplex virotherapy, indicating that molecular mechanisms lay at the center of this phenotypic resistance to therapy." (PMID 34696274, 2021). "In a recent study, hypoxia stimulated tumour-derived exosome secretion promoted oxidative phosphorylation in TAMs by transferring let-7a miRNA and by suppressing the insulin-Akt-mTOR pathway." (PMID 34193120, 2021). "At the same time, this signaling pathway can also be regulated by tumor suppressor genes such as PTEN.PI3K/AKT/mTOR contributes to tumor growth, angiogenesis, metastasis and drug resistance in many cell lines and mouse xenograft models." (PMID 33540155, 2021). "Knockout of CISH gene in NK cells stimulates mTOR signaling and increases NK cell metabolic fitness, which further improves their anti-tumor ability." (PMID 34742349, 2021).
tumor (continued). "For instance, circ-0072309 played anti-tumor roles by sponging miR-100 to block the phosphoinositide 3-kinase (PI3K)/protein kinase B (AKT)/mammalian target of rapamycin (mTOR) pathway signaling cascades, which are pivotal pathways in RCC development." (PMID 34604256, 2021). "MiRNA-99a was also found to directly target insulin-like growth factor 1 receptor (IGF-1R) and mTOR, suggesting that miR-99a is a promising tumor suppressor for HCC." (PMID 34582645, 2021). "This was promising as the index tumor (1a) was previously found by Tempus to have an overexpression of mTOR, supporting everolimus as a potential therapeutic target." (PMID 34943910, 2021). "Insulin and insulin‐like growth factors (IGFs) stimulate nutrient uptake by tumor cells through the PI3K/Akt/mTOR signaling pathway to promote proliferation." (PMID 34387383, 2021). "Phosphatase and tensin homolog (PTEN) is a tumour suppressor gene that negatively regulates the PI3K/Akt/mTOR pathway." (PMID 34099013, 2021). "At present, there have been third-generation mTOR inhibitors targeting more mTOR molecule binding sites, aiming at reducing tumor resistance through stronger binding with mTOR molecules." (PMID 34194607, 2021). "LKB1/AMPK pathway activation inhibits the mammalian target of rapamycin (mTOR), which negatively affects protein synthesis in tumor cells." (PMID 34745255, 2021). "Autophagy‐associated signalling pathways, including the ERK1/2 pathway, PI3K/AKT/ mTOR pathway and NF‐κB pathway, act as tumour suppressors or protect tumour cells against chemotherapy/radiotherapy‐induced cytotoxicity in gliomagenesis." (PMID 34632655, 2021). "When the glycolysis process is inhibited, intracellular AMPK levels are activated by phosphorylation, and activated AMPK inhibits protein synthesis and translation by inhibiting mTOR, which in turn inhibits tumor growth and metastasis." (PMID 34465340, 2021). "Surgical tumor samples among the cases were immunostained for p-mTOR (Ser2448) and classified as p-mTOR-overexpressed, if the expression level ≥ 75th percentile, or p-mTOR-negative/low otherwise." (PMID 34330319, 2021). "In hepatocellular carcinoma, tumor cell-intrinsic PD-1 can active mTOR pathway, which binds to the downstream target molecules S6 and eIF4E and promotes their phosphorylation, thus promoting tumor progression independently from specific immunity." (PMID 34326692, 2021). "The miR-200 family is implicated in the PI3K/AKT/mTOR signaling pathway, at least in part through downregulation of the PTEN tumor suppressor." (PMID 33800944, 2021). "Tumour-derived exosomal miR-499a-5p has diagnostic and therapeutic value and promotes EMT via the mTOR signalling pathway in lung cancer." (PMID 34193120, 2021). "We further identified that sensitivity to zotatifin in FGFR1/2 or HER2 driven tumor models is dependent on the activation state of the mTOR signaling pathway." (PMID 34900714, 2021). "TGF-β-mediated upregulation of mTOR resultes in the activation of hypoxia-inducible factor-1α (HIF-1α) that induces CD39/CD73 expression on tumor-infiltrating MDSCs." (PMID 35250965, 2021). "At the layer downstream of Akt, the most common deregulated mechanisms involve the effector target mTOR, responsible for tumour growth progression, as in endometrial malignancies." (PMID 34439105, 2021). "Tumor responses to an mTOR inhibitor and pan-AKT inhibitor have been seen in a PDTX mouse model of human OSA with either PTEN loss or AKT1 gain." (PMID 33556121, 2021). "In fact, experimental data have shown mTOR to be overexpressed in a significant proportion of HCCs and mTOR inhibitors to exert tumor suppressive effects in HCC cells." (PMID 33804480, 2021).
tumor (continued). "Phosphorylation of Akt-Ser473 and PRAS40-Thr246 activate mTOR signaling that affects diverse biologic aspects of the epithelial cells and other cells of tumor microenvironment." (PMID 33446797, 2021). "Rapalogs, ATP-competitive inhibitors, PI3K/mTOR dual inhibitors, and RapaLink have all been evaluated in pre-clinical and clinical studies of various types of tumours." (PMID 34309456, 2021). "Negative regulators of mTOR signaling, such as LKB1 and PTEN, are frequently mutated in LC and are considered tumor suppressors." (PMID 34135756, 2021). "TSC is caused by mutations in two genes: TSC1 (hamartin gene, 9q34) and TSC2 (tuberin gene, 16p13.3) that act as tumor suppressors inhibiting the mammalian target of rapamycin (mTOR)." (PMID 33669772, 2021). "AMPK phosphorylates and inhibits the pro-proliferative kinase mTOR and, thus, inhibits tumor cell proliferation and survival." (PMID 33507880, 2021). "We found that the two KEGG pathways most significantly enriched for in subtype-1 tumours were those involving thermogenesis and mTOR signalling." (PMID 34506537, 2021). "Adenosine, whose production from ATP and AMP is enhanced in the presence of Treg, affects tumor development by activating PI3K/Akt/mTOR pathway and upregulating metalloproteinases that stimulate invasiveness and migration capacity of malignant cells." (PMID 34071442, 2021). "Studies have shown that mTOR signal inhibition blocks tumor cell progression, disrupts angiogenesis, and induces apoptosis and autophagy." (PMID 34249899, 2021). "The PI3K/AKT/mTOR pathway is not only involved in cell proliferation and apoptosis but also plays an important role in tumor proliferation and chemoresistance." (PMID 32038983, 2020). "In summary, mTOR is always stimulated in tumors to maintain the growth, survival and proliferation of tumor cells, and plays a key role in tumor cell biology." (PMID 32175074, 2020). "This hamartin-tuberin complex regulates the mammalian target of Rapamycin (mTOR), which acts as a tumour-growth suppressor, controlling the cell growth and proliferation." (PMID 32972027, 2020). "MEF2D, Ezrin, and mTOR are other possible targets of miR-144 that inversely upregulate in OS, suggesting the critical role of miR-144 in the suppression of tumor growth and metastasis." (PMID 32276343, 2020). "CD164 has also been found to promote lung tumor-initiating cells with stem cell activity and determine tumor growth and drug resistance via Akt/mTOR signaling." (PMID 32364222, 2020). "The mTOR inhibitor Rapamycin has tumor inhibitory properties; and it is also used as an immunosuppressive agent after organ transplantation." (PMID 32635337, 2020). "For example, we identified at least four different dual PI3K and mTOR inhibitors of this pathway that have been used across the different tumour types." (PMID 32443649, 2020). "A more intense analysis of the transcriptome in the tissue samples demonstrates, that mTOR inhibition selectively affects tumor cells since tumor specific target genes e.g., Sct, Chga, and Chgb or Thp1 were reduced." (PMID 32373532, 2020). "For example, miR-203 functions as a tumor metastasis suppressor through inactivating the ERBB4/PIK3R3/mTOR/S6K2 signaling pathway, and miR-203 overexpression inhibited NSCLC metastasis in vitro and in vivo." (PMID 32206066, 2020). "mTOR pathway expression was more intense at the tumor edge where cellular growth and proliferation are more intense." (PMID 32070029, 2020). "Through the mechanistic target of rapamycin kinase (mTOR) inhibition, TAMs from hypoxic areas show a decrease in glycolysis and increase in endothelial glucose availability, thereby disturbing a compact tumor vasculature to undergo invasion and metastasis." (PMID 32219066, 2020).